BAG3 (BAG cochaperone 3)
Diseases named in the same sentence as BAG3 in open-access papers (continued):
Sharing a sentence is not in itself a finding about the gene and the disease.
cancer (continued). "The same study analyzed the effect of BAG3 overexpression and lentiviral depletion using one (notably male) cancer cell line." (PMID 32121220, 2020). "Due to its relevance in the regulation of key pathways, the dysfunction or deregulation of BAG3, as observed in cancer, myopathies, and age-related neurodegenerative disorders, has a devastating effect on cells and tissues." (PMID 33158300, 2020). "Evidence obtained in recent years underscores the fact that BAG3 drives several key hallmarks of cancer, including cell adhesion, metastasis, angiogenesis, enhanced autophagic activity, and apoptosis inhibition." (PMID 32121220, 2020). "This study identified BAG3 as a potential target for combined cancer therapies with Bcl2-antagonists." (PMID 32121220, 2020). "The HSP70 co-chaperone BAG3 is ubiquitously expressed at low levels; a highly constitutive expression of BAG3 was found in myocytes of cardiac and skeletal muscles as well as in cells of various cancer types." (PMID 33158300, 2020). "Regarding its proven implication in severe diseases such as cancer, myopathies and neurodegenerative disorders, the herein revealed new aspects of BAG3 function and the BAG3 pathway emphasize the potential of BAG3 as a therapeutic target." (PMID 33158300, 2020). "The homeostatic, cytoprotective function of BAG3-dependent autophagy so far has mostly been studied in models of neurodegeneration and its possible role in cancer is only beginning to emerge." (PMID 32121220, 2020). "Future investigations on the molecular events involved in BAG3-dependent regulation of the crosstalk between apoptosis and autophagy will be crucial to better understand the responses of individual cancers to therapy." (PMID 32121220, 2020). "This review provides a state-of-the-art overview on the role of BAG3 in stress and therapy resistance of cancer, with a particular focus on BAG3-dependent modulation of apoptotic signaling and autophagic/lysosomal activity." (PMID 32121220, 2020). "BAG3 is assigned a role in sustaining the growth of some tumor types and its expression is correlated with the poor prognosis of some cancers including PDAC." (PMID 31001483, 2019). "BAG3 functions as an anti-apoptosis protein through binding with Bcl-2 and overexpression of BAG3 in cancer cells contributes to resistance to chemotherapy." (PMID 31114002, 2019). "JG-98 disrupts HSPAs interaction with the co-chaperone BAG3 and affects signaling pathways important for cancer development." (PMID 31591429, 2019). "BAG3 is thought to play a key role in the development of a wide variety of diseases, including cancer." (PMID 30744164, 2019). "BAG3 silencing in cancer cells reduces invasion and our proteomics study in 8505C cell line and IPA data analysis are in agreement with this activity." (PMID 29487711, 2018). "Overall this study demonstrate that JG-98 series of compounds have multiple effects on cancer-related signaling pathways via both Bag3-dependent and –independent mechanisms." (PMID 29445088, 2018). "We investigated the entire set of proteins modulated by BAG3 silencing in the human anaplastic thyroid 8505C cancer cells by using the Stable-Isotope Labeling by Amino acids in Cell culture strategy combined with mass spectrometry analysis." (PMID 29487711, 2018). "They disrupt Hsp70 interaction with a co-chaperone Bag3 and affect signaling pathways important for cancer development." (PMID 29445088, 2018). "In this study we investigated a role for BAG3 in driving cancer cell proliferation in TNBC models by stabilising EGFR signalling nodes." (PMID 29644001, 2018). "Accordingly to the role of BAG3 in cancer proliferation and apoptosis, we found up-regulation of 5 pro-apoptotic proteins and down-regulation of 3 anti-apoptotic proteins in BAG3-silenced cells." (PMID 29487711, 2018).
cancer (continued). "BAG3 has also been shown to regulate cell proliferation and motility in different cancer cell lines by regulating the migratory cellular phenotype through interaction with SH3 domain-containing proteins involved in focal adhesion formation." (PMID 29644001, 2018). "BAG3 is expressed in many cancers and correlated with the poor prognosis of some cancers, including pancreatic." (PMID 30154469, 2018). "Many recent studies discuss BAG3 as a potential promising target not only for anti-cancer therapy, but also for the therapy of diseases like neurodegenerative disorders or myopathies." (PMID 28680391, 2017). "A vast number of studies addressing the anti-apoptotic, pro-survival activity of BAG3 in cancer were published." (PMID 28680391, 2017). "BAG3 is also highly expressed in many hepatocellular carcinomas and promotes invasiveness and angiogenesis in these cancer cells." (PMID 28680391, 2017). "In the following, only some recent studies are exemplarily listed to illustrate the significance of BAG3 for cancer biology." (PMID 28680391, 2017). "A second major role for BAG3 is that it inhibits apoptosis through multiple mechanisms—many of which have been elucidated in cancer cells." (PMID 25925243, 2015). "For example, phosphorylation of Ser187 of BAG3 by protein kinase C delta (PKCΔ) leads to increased epithelial-mesenchymal transition, motility and invasiveness of cancer cells." (PMID 25925243, 2015). "The BAG3-HSP protein–protein interaction is increasingly recognized as a therapeutic target in the treatment of cancer." (PMID 25925243, 2015). "BAG3 is found in the serum of pancreatic cancer patients and can beused as a marker of disease, but its role in cancer is unclear." (PMID 26522614, 2015). "Hsp70 cochaperones Bag1, Bag3, and Hop play significant roles in the etiology of some cancers as do Hsp90 cochaperones Aha1, p23, Cdc37, and FKBP1." (PMID 24278769, 2013). "Elevated expression of Bag1 and Bag3 in each case signals a poor prognosis for cancer bearing patients." (PMID 24278769, 2013). "The need for dual regulation of BAG3 in apoptosis suggests a key role for BAG3 in cancer cell resistance to apoptosis." (PMID 19352495, 2009). "MDA435 and HeLa human cancer cell lines exposed to STS underwent apoptosis with a concomitant time and dose-dependent loss of BAG3, suggesting the survival role of BAG3 was subject to STS regulation." (PMID 19352495, 2009). "The need for this dual and sequential regulation of BAG3 suggests a selective survival role of BAG3 in the cancer cells." (PMID 19352495, 2009). "On the other hand, the most frequently down regulated AM genes are TGFBR2 (7/13 of cancer models), BAG3, CLU, LGALS1, LTBR, SGK (in 6/13)." (PMID 19402918, 2009). "It further suggests that impaired BAG3 degradation is central in the protection of cancer cells against intrinsic apoptotic pathway stress." (PMID 19352495, 2009). "BAG3 contributes to tumor progression through several mechanisms, including anti-apoptotic activity, chemoresistance, promotion of tumor invasiveness, and maintenance of cancer stem cells." (PMID 40507324, 2025). "This cohort study found that common missense variants in TTN and BAG3, previously associated with a lower risk of sporadic DCM in the general population, were also associated with a reduced risk of late-onset CCM among childhood cancer survivors." (PMID 40540274, 2025). "Furthermore, the present work demonstrates that BAG3 is actively secreted by diverse human cancer cell lines, thereby extending previous knowledge that primarily focused on intracellular expression." (PMID 41367874, 2025). "Additionally, lncRNA‐SNHG15 has been identified as a regulator of downstream genes such as MYC, NRAS, BAG3, and ERBB3, all of which are closely associated with cancer progression." (PMID 40620190, 2025).
cancer (continued). "Similarly, abnormal BAG3 expression has the potential to serve as a marker for tumorigenesis, invasiveness, and prognosis, providing a new avenue for the treatment of cancers." (PMID 39944833, 2025). "Additionally, we measured BAG3 protein levels in serum samples from patients with various carcinomas." (PMID 41367874, 2025). "Moreover, elevated serum BAG3 levels in carcinoma patients compared to healthy controls further support its potential as a biomarker for disease presence and activity." (PMID 41367874, 2025). "In low-grade cancer, BAG3 displayed a positive correlation (r = 0.523) with Contrast T2WI." (PMID 38791417, 2024). "Some studies have previously indicated that BAG3 promotes the stem cell character of cancer cells." (PMID 38655699, 2024). "Indeed, growing data in oncology highlights the critical role of BAG3 in promoting cancer cell proliferation and resilience." (PMID 39198407, 2024). "BAG3 is an essential regulator for regulating the proteome and maintaining cellular survival, and its role of BAG3 has been widely investigated in heart disease and cancer (Kirk, Cheung & Feldman, 2021)." (PMID 37576499, 2023). "In cancer cells, BAG3 binds to and supports multiple survival protein; therefore, it may be a promising therapeutic target." (PMID 37576499, 2023). "In this review we present an overview of the current literature surrounding BAG3 and its various roles in proteostasis, cardiac pathology, central nervous system disorders, cancer proliferation, and recently identified roles in maintaining the homeostasis of the mitochondria." (PMID 36980278, 2023). "A common feature of many cancer cells is the presence of normal or supra-normal levels of BAG3." (PMID 36980278, 2023). "Additionally, glutaminase (GLS), an enzyme that converts glutamine to glutamate, is involved in cancer cell metabolism, growth, and proliferation and in certain cancers is regulated by BAG3." (PMID 36980278, 2023). "Besides the nf-kb pathway, BAG3-Hsp70 interaction is additionally known to regulate metastasis and survival of cancer cells through pathways involving FoxM1 and HuR transcription factors." (PMID 36980278, 2023). "We have recently reviewed the role of BAG3 in cancer biology in detail, but will point out several cogent points here because the contrast is quite remarkable and gives further support to the concept that BAG3 is a quintessential multi-functional protein." (PMID 36980278, 2023). "In addition to BD, BAG3 also includes proline rich (PxxP) and WW modules responsible for its interaction with several signaling factors highly involved in cancer development." (PMID 35163936, 2022). "In addition, BAG3 has recently emerged as an attractive target in several pathological conditions, including cancer, driving the main hallmarks of malignancy, such as apoptosis suppression and oncogenic transformation." (PMID 35163936, 2022). "BAG3 plays a role in cancer also by modulating cell metabolism." (PMID 35203329, 2022). "BAG3 is another important BAG-family protein member in cancer progression." (PMID 34831344, 2021). "The experimental results demonstrated that the resultant nanocomplexes exhibited great NIR photothermal conversion ability and the cancer cells were more sensitive to heat with the help of BAG3-targeting siRNA oligomers, thus realizing both gene delivery and low-temperature PTT." (PMID 34041494, 2021). "The decrease in BAG3 expression leads to cancer cell apoptosis." (PMID 33773557, 2021). "HSF1 inhibition by using HSF1 shRNAs or KRIBB11 decreased the expression of HSF1 downstream proteins, such as HSP70 and HSP27, and also decreased the expression of HSP90/HSP70/BAG3 client proteins, such as BCL2, MCL1, EGFR, MET, and AXL, causing apoptosis of EGFR-TKI-resistant cancer cells." (PMID 34203709, 2021). "Moreover, BAG3 has been shown to be involved in spreading and migration in lymphoblasts as well as in motility and cell adhesion in various cancer cells." (PMID 33158300, 2020).
cancer (continued). "Of note, BAG3 secreted by cancer cells may activate macrophages and promote IL-6 production, suggesting that BAG3 may regulate inflammation also in the myocardial context." (PMID 32528937, 2020). "Moreover, a different approach has been proposed to inhibit BAG3 activity for cancer therapy using a small molecule." (PMID 30973679, 2019). "In addition, based on its initial description BAG3 is an anti-apoptotic protein that plays a decisive role in other widespread diseases, including cancer and myopathies." (PMID 28680391, 2017). "Therefore, in the search for novel therapeutic intervention avenues in neurodegeneration, myopathies and cancer BAG3 is a promising candidate." (PMID 28680391, 2017). "This review will focus on the role of the BAG3-mediated selective macroautophagy pathway as well as of the anti-apoptotic co-chaperone BAG3 (BCL-2-associated anthanogene 3) itself in cellular PQC and in severe diseases, including cancer and myopathies." (PMID 28680391, 2017). "From a mechanistic point of view, we identified down-regulation of Usp9X as well as Bag3 followed by enhanced Mcl-1-degradation as one of the driving mechanisms subjacent to the profound anti-cancer activity inherent to a combined inhibition of ERK signaling and Bcl-2/Bcl-xL." (PMID 26474387, 2015). "In human cancer cells, BAG3 protein is known to sustain cell survival." (PMID 23876161, 2013). "The two family members with most significance in cancer appear to be Bag1 and Bag3." (PMID 24278769, 2013). "Impairment of BAG3’s specific function to clear disease-related aggregate-prone proteins through chaperone-assisted selective autophagy (CASA) was implicated in various diseases, including age-related disorders such as Alzheimer’s disease, Huntington’s disease, cancer, and (cardio-)myopathies." (PMID 39562141, 2025). "In addition to its physiological role in protein quality control, BAG3 pathologically regulates a variety of different cancer characteristics, including cell growth and survival, angiogenesis, motility, and metastasis, as well as the enhancement of therapy resistance." (PMID 38655699, 2024). "In addition, HCA upregulates BAG3 expression and mediates apoptosis in cancer cells." (PMID 39684673, 2024). "However, abnormally expressed BAG3 can promote the malignant behavior of some cancers." (PMID 39215616, 2024). "Additionally, its distinct role in inhibiting BAG3 was shown in cancer cell lines." (PMID 35834635, 2022). "The binding of BAG3 to GLS prevented its proteosomal degradation, whereas autophagy was hypothesized to be induced via ammonia that is derived from glutaminolysis, as was shown previously, indicating that BAG3 is a central factor bridging cancer metabolism and autophagy." (PMID 32121220, 2020). "The established BAG3 interactomes comprise already known and annotated BAG3 interactors (cf. annotation in BioGRID, entry BAG3) that were found in other interactome studies performed in cancer cell lines, in immortalized cells or in post-mitotic cells, such as myocytes or neurons." (PMID 33158300, 2020). "Therefore, different types of cancer therapy may evoke distinct impacts on the BAG3-driven stress response regarding apoptosis vs. autophagy modulation." (PMID 32121220, 2020). "Therefore, given the high relevance of glutaminolysis for proliferating cancer cells, as well as involvement of BAG3 in regulation of glutaminolysis, BAG3 may become a therapeutic optional target against cancer." (PMID 30910998, 2019). "In fact recently, the first selective BAG domain modulator of BAG3 has been proposed as a novel candidate for the development of a new class of chemotherapeutic agents; this 2,4‐thiazolidinedione derivative, by interfering with the binding between BAG3 and Hsp70, reduces cancer cell proliferation." (PMID 30973679, 2019).
cancer (continued). "Moreover since severalother cancer types express intracellular BAG3 (refs 20,21), they might also release it to theextracellular environment, extending the potential of the therapeutic use ofBAG3-blocking antibody." (PMID 26522614, 2015). "Elucidation of the precise mechanism involved should contribute to further our understanding of the apparent addiction of some cancer cells to the co-chaperone activity of BAG3 that might support uncontrolled cell division in the face of high mitotic stress experienced by most malignant cells." (PMID 26496431, 2015). "The objective is to analyze BAG3 expression across various HNSCC types and correlate it with disease-free survival (DFS), aiming to elucidate the influence of BAG3 positivity on cancer progression." (PMID 40507324, 2025). "Despite differences in the chemical properties of bortezomib, MG-132, and MLN-2238, treatment with these PIs led to the recurrent dysregulation of 12 genes (e.g. BAG3, DNAJB1, HMOX1) in cell lines representing multiple cancer types." (PMID 39138277, 2024). "HSF1 influences apoptosis and chemoresistance through its interactions with co-chaperones like BAG3 and BAG1 and it promotes cell survival by upregulating pro-survival BCL-2 family proteins and HSPs across various cancer types." (PMID 39850800, 2024). "For example, previous studies reported that cochaperones DNAJ, Bag3, Bim, and CHIP can form context-dependent PPIs with Hsp70 to sustain survival in different cancer types." (PMID 38409088, 2024). "BAG3 also has the ability to enhance epithelial-mesenchymal transition (EMT), which enables cancer cells to invade surrounding tissues." (PMID 36980278, 2023). "TRAF7 has been partially studied in aquatic animals, and BAG3, WDR20 and FUT4 are mostly focused on wound tissue recovery and cancer treatment in medicine." (PMID 35936896, 2022). "LncRNA-SNHG15 regulated the expression of downstream genes including MYC, NRAS, BAG3, and ERBB3, which are closely related to cancer progression." (PMID 35617032, 2022). "KRIBB11 effectively decreased the HSP70/BAG3/BCL2 and EGFR/MET/AXL proteins, leading to apoptosis of resistant cancer cells." (PMID 34203709, 2021). "In complex with HSP70, BAG3 has already been shown to interact with the SH3 domain of SRC via its PxxP region, thus affecting SRC signaling pathway in cancer cells." (PMID 33158300, 2020). "Ectopic expression of BAG3 resulted in a strong increase in autophagy independently of Beclin or PI3K; instead, glutaminolysis, the breakdown of glutamine to feed cancer cell growth, was increased." (PMID 32121220, 2020). "Given the relevance of BAG3 for many other types of cancer, cancer cell proliferation, and therapy and stress resistance, other tumor entities may follow this line of research in the near future and cancer research may add BAG3 to the list of potential therapeutic and diagnostic markers." (PMID 32121220, 2020). "We here report that through the release of BAG3, PDAC cells stimulate macrophageactivation and the release of cancer cell-sustaining factors." (PMID 26522614, 2015). "Importantly, among three miRNAs, only miR-570 showed partial complemental with 3′-UTR sequences in not only human HSPA1A and BAG3 but also HSPA1B and HSP90AA1 (highlighted in red), which are involved in cancer progression." (PMID 36114410, 2022).